TLR4 (toll like receptor 4)
Diseases named in the same sentence as TLR4 in open-access papers (continued):
Sharing a sentence is not in itself a finding about the gene and the disease.
viral infection (continued). "However, there is accumulating evidence that TLR4 is also involved in viral infections and contributes to the immune escape of MV and other viruses." (PMID 29368634, 2018). "The TLR4 translocation change was examined after viral infection." (PMID 30419930, 2018). "Whereas host DAMPs might play a central role in acute lung injury and are detected in the lungs of patients with severe IAV or SARS-CoV infections, the role of DAMP-mediated TLR4 activation in other viral infections remains largely unexplored." (PMID 30571771, 2018). "One potential benefit to activating TLR4 during viral infection might be to induce specific host factors that promote viral replication or repress those with antiviral activity." (PMID 30571771, 2018). "Treatment with TLR4 antagonists has consistently resulted in reduced cytokine and chemokine production and mitigated disease symptoms in small animal models of IAV, EBOV, and DENV infections, clearly identifying a role for TLR4 activation in the pathogenesis of these viral diseases." (PMID 30571771, 2018). "Given the high mutation rate of RNA viruses that enables them to escape from challenging host responses, the question arises whether the activation of TLR4 is beneficial for a productive viral infection." (PMID 30571771, 2018). "As a result, TLR4 is involved in the pathogenesis of various viral infections." (PMID 26347404, 2015). "It is documented that TLR2 and TLR4 recognize viral capsid proteins and envelope glycoproteins in measles virus, hepatitis C virus, murine leukemia virus, mouse mammary tumor virus and coxsackievirus B4 virus infections." (PMID 23671700, 2013). "Innate cellular signaling in response to viral infection is cell-type dependent and we have recently shown that, in the context of hMVP infection, TLR-4 and RIG-I play a major role in viral-induced signaling in immune cells and airway epithelial cells, respectively." (PMID 23626834, 2013). "Interestingly, replication of HIV-1 in IM-MDDCs was still enhanced by the TLR2 ligand at an early time point following virus infection while engagement of TLR4 led to a potent inhibition of virus production." (PMID 19419540, 2009). "Accordingly, TLR4 mutations (Asp299Gly and Thr399IIe) may be associated with increased risk of severe RSV bronchiolitis in human infants, thus implicating a role of TLR4 in this virus infection." (PMID 16827942, 2006). "Therefore, believe that this viral infection and the subsequent organ damage may stimulate the toll-like receptor 4 (TLR4) pathways, increasing inflammatory cytokine production." (PMID 38165854, 2024). "There is also evidence that there may be an increase in TLR4 production in viral infections." (PMID 37513727, 2023). "Moreover, siRNA-mediated gene silencing could be explored as a suitable tool to investigate the detailed role of TLR4 during viral infection." (PMID 37153546, 2023). "Although the TLR4 complex is a major sensor of Gram-negative bacterial LPS, it can also be activated by various endogenous danger-associated molecules (DAMPs) released from lytic cells during host tissue injury or viral infection." (PMID 36678520, 2022). "Additionally, TLR4 can modulate the activation of type I IFN genes through other ways associated with TRIF, where TLR4 interacts with TRIF through TRAM, triggering a late activation of the MYD88 pathway, and the expression of type I IFN genes against viral infection." (PMID 32765522, 2020). "At this time, we do not know how Eritoran blocks release of HMGB1 into serum after virus infection; however, we hypothesize that epithelial necroptosis caused by influenza virus infection leads to release of HMGB1 that, in turn, engages TLR4 and can be blocked by both Eritoran and P5779." (PMID 29535197, 2018).
viral infection (continued). "However, somewhat surprisingly, the ablation of TLR4 molecule resulted in a highly increased number of CD11cintPDCA-1high plasmacytoid DC (pDC) subset, which is known as a potent cellular component to produce type I IFNs in response to viral infection." (PMID 25188232, 2014). "Future research will have to delineate whether some of the reported virus-induced immune responses mediated via TLR2 and TLR4 are due to recognition of DAMPs rather than direct recognition of the viruses, and thus further characterize the role of TLR2 and TLR4 during virus infection in humans." (PMID 23435233, 2013). "To further evaluate whether TLR4 is involved in expression of cytokines induced by viral infection, we collected the supernatants from above transfected and viral infected cell cultures at 1 h p.i. or 4 h p.i. and measured expression of IL-6 and IFN- β by ELISA assays." (PMID 24278275, 2013). "Meanwhile, the protein levels of upstream TLR4 (bacterial infection response), TLR9 (viral infection response) and downstream iNOS were also inhibited synchronously." (PMID 39911394, 2025). "The specific mechanisms include the outer membrane products of Bacteroides species binding to Toll-like receptor 4 (TLR4) on colonic dendritic cells (DCs), inducing the secretion of IFN-β, thereby effectively resisting influenza and other viral infections." (PMID 40863240, 2025). "For the first time, we integrated these findings and demonstrated that during recombinant virus infection, HMGB1 binds to TLR4 on macrophages, activating the MyD88-NFκB-NLRP3 (ASC) pathway and inducing M1 polarization." (PMID 40082916, 2025). "ATRA alone upregulated TLR3, TLR4 and RIG-I intestinal epithelial cells, however it suppressed TLR3, TLR7 and RIG-I expression following viral infections." (PMID 40666513, 2025). "Firstly, the outer membrane products of Bacteroides can activate colonic DCs through TLR4, promoting the secretion of IFN-β and resisting systemic viral infections, such as influenza." (PMID 40863240, 2025). "This underscores the complexity of alternative splicing of TLR4 and JAK3 and its potential significance in the context of viral infections." (PMID 38414855, 2024). "The grass carp’s TLR4 gene expression increases in the liver and muscle tissues infected with GCRV, suggesting it protects against viral infections." (PMID 39483482, 2024). "More specifically, Bacteroides glycolipids can activate colonic dendritic cells to secrete IFN-β through TLR4-TRIF, thereby enhancing host resistance to viral infection." (PMID 38388458, 2024). "The activation of TLR4 triggers MyD88 and TRIF-dependent signaling pathways in a coordinated manner, allowing for a comprehensive immune defense against both bacterial and viral infections from various sources." (PMID 38694821, 2024). "The present study raises the possibility that bacterial and viral infection through activation of TLR-3, TLR-4 and TLR-7/8, have the potential to alter fetal brain protection." (PMID 36721242, 2023). "TLR4 is a member of the TLR family, related to the infection of various viruses and involved in the occurrence of viral diseases." (PMID 36500406, 2022). "Besides, selected probiotic strains also showed no NF‐κB activity via TLR5 and TLR9, thus excluding other TLR signalling, since lactic acid bacteria and bifidobacteria do not possess LPS (TLR4 signalization) and the remaining TLRs are associated mainly with viral infections." (PMID 32945079, 2021). "TLR4 signalling is essential for the secretion of the antiviral cytokine IFN-β, which also reduces (cardiac) inflammation and helps control the viral infection." (PMID 33505220, 2021). "The viral infection led to significant overexpression of PRR genes, mainly DDX58, IFIH1, TLR2, and TLR4." (PMID 34937196, 2021). "The map illustrates that HSPA8 and proteins in subnetworks, such as EIF2AK3, TLR4, NFKB1, BAK1, and RelA, are enriched in viral infection of several viruses." (PMID 34769416, 2021).
viral infection (continued). "Several studies have shown that the secretion of TLR-3, TLR-4, TLR-7, TLR-9, and TLR-10 genes from hepatic tissue was upregulated in some viral infection models, and GA or GL is capable of inhibiting these receptors." (PMID 33505216, 2021). "To sum up, we propose a TLR4-mediated cascade in the development of APN in B7.2 (L31) transgenic mice and its clinical relevance in viral infection triggered GBS." (PMID 33752705, 2021). "Viral infections trigger the production of pro-inflammatory cytokines, particularly IL-1β and TNF-α, in human pancreatic cells through a TLR4-dependent pathway." (PMID 33071971, 2020). "Taken together, these data demonstrate that TREM2 knockdown decreases cytokine-mediated CD163 expression to inhibit virus infection via Syk/PI3K and TLR4/NF-κB signaling." (PMID 32401783, 2020). "Previously, respiratory syncytial virus (RSV) was reported to induce Toll-like receptor 4 (TLR4)-mediated activation of p38 in the early stages of infection, which was important for viral infection." (PMID 31963532, 2020). "TRIF has been shown to form a complex with TBK-1, a protein kinase that has been reported to directly phosphorylate IRF-3 and IRF-7 in response to viral infection or TLR3 and TLR4 stimulation based on in vitro kinase assays." (PMID 32373120, 2020). "In this study, we focused on TLR1, TLR2, TLR4, TLR5, TLR6 and TLR9 expression fold changes in two genital epithelial cells (HEC-1-A and VK2) after viral infection." (PMID 30419930, 2018). "TLR-3 is known to play a key role in the host response to virus infection by recognizing virus-derived dsRNA in intracellular vesicles to induce the production of IFN, whereas TLR-4 recognizes viral structural proteins on the plasma membrane." (PMID 29312337, 2017). "HMGB1 inhibitor or neutralizing antibody also abates immune response to virus infection and tumor antigen via blocking HMGB1/TLR4 signaling pathway." (PMID 28969092, 2017). "TLR-3 is known to play a key role in the host response to virus infection by detecting virus-derived dsRNA in intracellular vesicles, whereas TLR-2 and TLR-4 recognise viral structural proteins on the plasma membrane." (PMID 25973612, 2015). "In viral infection, four TLRs, including TLR3, TLR7, TLR8 and TLR9, seem to play critical roles in the recognition of viral nucleic acid components, and TLR2 and TLR4 were shown to detect viral components such as envelope glycoproteins." (PMID 25188232, 2014). "Both TLR2 and TLR4 have been associated with recognition of DAMPs released from necrotic infections, including heat shock proteins (HSPs), high mobility group box-1 (HMGB1) protein, and oxidized phospholipids, all of which may be released during virus infections." (PMID 23435233, 2013). "TLR4, TLR5, TLR15, and TLR16 belong to the TLR family and are involved in sensing and initiating immune responses to viral infection." (PMID 24168272, 2013). "Viral infections, by RSV or influenza A, have been shown to upregulate TLR-3 and TLR-4 expression in host airway epithelial cells, leading to increased signalling activity and proinflammatory cytokine production." (PMID 19505311, 2009). "TLR4, and TLR5 are not involved in the recognition of viral nucleic acids, however they recognize viral proteins and GM related antigens caused by viral infection, such as LPS (TLR4 ligand) and flagellin (TLR5 ligand)." (PMID 37928517, 2023). "The study also suggests that TLR4 inhibition has no role in post-entry stages of viral infection i.e. viral transcription, replication and translation inside the host macrophages." (PMID 37153546, 2023). "The viral-infection-mediated release of HMGB1 triggers pro-inflammatory responses similar to those of LPS and thus supports the significance of the therapeutic potential of TLR4/MD-2 antagonists for symptom release in viral disease." (PMID 36678520, 2022).
viral infection (continued). "Although viruses are detected by other PRRs than TLR4 (TLR3, 7, 8, RIG-I), in the more severe outcomes of viral infection such as acute lung injury (ALI), TLR4 signaling is crucially involved through the generation of oxidized phospholipids (OxPAPC) which can also activate TLR4." (PMID 36678520, 2022). "These phenomena could be due to the fact that DVP-1 strengthened the organic immunity by stimulating the TLR4/MyD88/NF-κB signaling pathway by which more cytokines, such as IL-1β, IL-4, IL-6, and TNF-α, were generated and released before the viral infection." (PMID 36177044, 2022). "TLR4 can also influence the stimulation of type I IFN genes through other TRIF-related mechanisms, such as when TLR4 interacts with TRIF via TRAM, resulting in a late stimulation of the MYD88 pathway and the production of type I IFN genes in response to viral infection." (PMID 36703982, 2022). "Furthermore, treatment with these TLR4 antagonists prevented lethal EBOV and IAV infection in mice demonstrating the therapeutic potential of inhibiting TLR4 during viral infections." (PMID 33487119, 2021). "A study demonstrated that GA was not capable of influencing TLR-4 gene secretion during viral infection." (PMID 33505216, 2021). "At 48 h post-infection (hpi), growth media was replaced to remove potential inflammatory cytokines released as a response to the early phase of the virus infection, and NLRP3 inflammasome assembly and activation induced by the classical TLR4 agonist LPS, and ATP." (PMID 31849970, 2019). "Expression of those receptors sensitizes endothelial cells to the action of several Gram-negative (Tlr4) and positive (Tlr2) bacteria along with several viral infections (Tlr3)." (PMID 32038494, 2019). "We also determined the effect of viral infection on TLR4 expression change via western blot, and illustrated that HSV-2 infection could up-regulate TLR4 expression in protein level." (PMID 30419930, 2018). "Indeed, viral proteins, similar to viral nucleic acids or replication intermediates, can in some cases also function as PAMPs, specifically recognized by certain host PRRs, such as TLR2 and TLR4, to modulate the IFN responses during viral infection." (PMID 28848548, 2017). "Thus, increased expression of TLR4 and CD14 in PBMCs cannot be explained by a simple increase in monocyte frequency following viral infection." (PMID 22435642, 2012). "The present work, together with findings from previous studies of our group, indicates that Dectin-1, TLR2, and TLR4 are important PRRs for the activity of MDSCs in pulmonary PCM, as already demonstrated in cancer and other diseases, such as other fungal, bacterial, and viral infections." (PMID 39035356, 2024). "Subsequently, TLR4 internalizes into the endosomal membrane, predominantly relying on TRIF to initiate the IFN response and transmit signals to antigen-presenting cells, playing a crucial role in defending against viral infections and initiating the subsequently acquired immunity." (PMID 38694821, 2024). "In an infectious vesicular stomatitis virus (VSV) model, peritoneal macrophages (PMs) exposed to a viral infection could form LF/LPS complexes and initiate a TLR-4-dependent signal pathway, inducing IFN-α/β production and viral infection remission, upon the addition of LF." (PMID 38254678, 2024). "Galectin-3 is also an agonist of Toll-like receptor 4 (TLR4) and can regulate the NOD-like receptor family pyrin domain containing 3 (NLRP3) inflammasome, promoting inflammasome assembly and activation, which contributes to enhanced inflammation and tissue damage in viral infections." (PMID 37298569, 2023). "However, another studie also showed that B. fragilis played a protective role in viral infection through TLR4-induced IFN-β secretion, which was independent of TLR226." (PMID 37740010, 2023).
viral infection (continued). "Also, Candida cell wall components may bind to toll-like receptors (TLRs), primarily TLR-2 and TLR-4, inducing the production of tumor necrosis factor (TNF)-α and type I IFNs that eliminate viral infections." (PMID 37573268, 2023). "As our results showed, increased TLR4 expression was detected in the spleens of the mice infected with SIV, and the elevation of TLR4 for at least 5 weeks after SIV infection, which meant that the innate immune responses were continuously activated to resist viral infection." (PMID 35003038, 2021). "To demonstrate that TREM2 knockdown reduces cytokine-mediated CD163 expression to inhibit virus infection via Syk/PI3K and TLR4/NF-κB signaling, we first explored whether TREM2 knockdown promotes the expression of proinflammatory cytokines and type I interferons via these pathways." (PMID 32401783, 2020). "The lack of response in HPV+ lines may suggest changes in the TLR4 signaling pathway as a consequence of viral infection." (PMID 29416610, 2018). "Our findings indicate that ProTα variants strongly inhibit viral replication mainly, but not exclusively, through TLR4 signaling and that they are released within minutes of viral infection suggesting that they may function as DAMPs." (PMID 27310139, 2016). "It is noteworthy that in our recent study we found that Tlr4−/− mice also exhibited reduced PMN recruitment into the splenic MZ and failed to clear the virus from the spleen, when analyzed for the amounts of Ad DNA present 24 hours after virus infection by real-time PCR." (PMID 24651866, 2014). "However, the only TLRs that utilize TRIF are TLR3 and TLR4 and the former is likely not involved in C. koseri recognition since its ligand, dsRNA, is typical of viral infections." (PMID 21496301, 2011). "IFITM3 is induced by viral infection and cytokines, it is likely that it acts downstream of cytokine activation, which may partly explain why its overexpression does not impact inflammatory activation and signaling mediators TLR4 and NF-κB." (PMID 37602193, 2023). "For instance, TLR4 can remember LPS from Gram-negative bacteria, but TLR3 is known to recognize dsRNA that is generally generated during viral infections." (PMID 39483482, 2024). "LY6E downregulates CD14, a key molecule in the TLR4/CD14/NF-κB pathway, inducing a negative feedback loop for innate immune activation and providing a new pathway for viral infection." (PMID 38169284, 2024). "Unlike TLR4, the lung expression of AGER is mainly localized to alveolar epithelial cells and plays an important role in various lung diseases that include viral infections." (PMID 33313438, 2020). "In particular, it prevented viral infection by improving the host’s nonspecific immunity and antioxidation capacity, thus inhibiting several pathways related to viral infection, including MAPK, PI3K-AKT, TLR4/8, NF-κB, and Nrf-2/hemeoxygenase-1." (PMID 39011148, 2024). "However, some specific responses to stimulation of TLR4 or TLR3 and RIG-I like receptor were detected that have not previously been annotated as specific for bacterial and viral infection in swine." (PMID 32973863, 2020). "The result was that unlike TLR4, MD2 expression was not up-regulated during the viral infection." (PMID 30419930, 2018). "In addition, the red gene signature includes TLR2, TLR4, and TLR8, which are not prominent pDC receptors but may play a role in pDC activation under specific conditions, such as during viral infection or in inflamed tissues." (PMID 31552042, 2019).